KRAS (KRas proto-oncogene, GTPase)
Diseases named in the same sentence as KRAS in open-access papers (continued):
Sharing a sentence is not in itself a finding about the gene and the disease.
adenocarcinoma (continued). "Colonoscopy confirmed a 25-mm type 2 tumor in the transverse colon, which was diagnosed as a well-differentiated adenocarcinoma with wild-type KRAS on histopathological examination." (PMID 28228152, 2017). "We demonstrated that PD-L1 enhancer activity is driven by AP-1 under MAPK signaling and the binding of cJUN to the candidate AP-1 site in a human KRAS-mutant adenocarcinoma cell line." (PMID 27846317, 2016). "Fifty percent of adenocarcinomas with clear cell component (11/22) harbored EGFR mutation, 41 percent (9/22) harbored KRAS mutation and 5 percent (1/22) harbored AKT1 mutation." (PMID 27013585, 2016). "The human adenocarcinoma cell line SW480, which harbors the KRAS G12V mutation in homozygosis, was used to assess the analytical sensitivity of the assay." (PMID 27043547, 2016). "KRAS mutations were identified in 32% of the NSCLC patients, which mainly included adenocarcinoma patients." (PMID 27008036, 2016). "They identified 17 microRNAs that were differentially expressed between EGFR-mutant and EGFR-wild-type adenocarcinomas, and three microRNAs differentially expressed between KRAS-mutant and KRAS-wild-type adenocarcinomas." (PMID 27005669, 2016). "In our study, we analyzed two common genomic alterations in adenocarcinomas of the lung: EGFR and KRAS mutations." (PMID 27145277, 2016). "Of the adenocarcinomas, 2,295 (46%) tumors had EGFR mutations, 358 (9.2%) had KRAS mutations, and 270 (7.2%) had ALK rearrangements." (PMID 26992209, 2016). "In contrast, KRAS mutations, despite ostensibly functioning just downstream of EGFR, tend to occur in adenocarcinomas with mucinous histology from male smokers." (PMID 26556242, 2015). "Molecular biological analysis of the 93 patients with adenocarcinoma showed 59 epidermal growth factor receptor (EGFR) mutations (63.4%), five KRAS mutations (5.4%) and four EML4-ALK rearrangements (4.3%)." (PMID 25621070, 2015). "We undertook a single-institution retrospective analysis of 93 consecutive patients with stage IV NSCLC adenocarcinoma with known KRAS and EGFR MT status to determine the association of KRAS MT with survival." (PMID 26471290, 2015). "We studied a consecutive series of patients with stage IV NSCLC adenocarcinoma and known EGFR and KRAS mutation status." (PMID 26471290, 2015). "Patients with PD-1 positive tumors tended to be male and/or smokers with KRAS-mutant adenocarcinoma." (PMID 26175921, 2015). "KRAS mutations were more frequently detected in CRC patients who were female (OR = 1.64) and 50 years old or older (OR = 4.17), and had adenocarcinoma (OR = 2.41)." (PMID 26081767, 2015). "Mutations (MT) of the KRAS gene are the most common mutation in non-small cell lung cancer (NSCLC), seen in about 20–25% of all adenocarcinomas." (PMID 26471290, 2015). "Another preclinical study based on shRNA screening identified BCL-XL and MEK inhibition as a potentially successful strategy for treatment of KRAS-mutant adenocarcinoma." (PMID 24722523, 2014). "The older group (≥80 years) of patients with NSCLC included significantly higher rates of non-adenocarcinoma, wild-type EGFR, KRAS mutations, and smokers." (PMID 25152277, 2014).
adenocarcinoma (continued). "In EGFR and KRAS-wild type adenocarcinomas (EGFRwt/KRASwt), different potential drivers of pathogenesis exist, including ALK, RET, and ROS1 gene fusions, with ALK rearrangements being therapeutically relevant." (PMID 24205279, 2013). "Together, this suggests that the overall genomic and transcriptional landscape of adenocarcinoma is affected, but only to a minor extent, by the mutational status of EGFR and KRAS." (PMID 24205279, 2013). "In adenocarcinoma, the mutational spectrum is dominated by EGFR and KRAS mutations, where the former is an established predictor of response to EGFR inhibitors." (PMID 24205279, 2013). "In the present study, we found that 10% of the 77 analyzed adenocarcinoma samples harbored EGFR mutations, 35% of which carried KRAS mutations, while 51% of the 54 samples analyzed for KRAS mutations were negative regarding both mutation types." (PMID 23817662, 2013). "In wild type KRAS/BRAF invasive adenocarcinomas with nuclear beta-catenin, increased c-MYC expression was associated with an up-regulation of SIRT1." (PMID 23045412, 2012). "In western countries, KRAS mutation rate is high in NSCLC patients, especially in those with adenocarcinoma (30%-50%), but EGFR mutation rate is low (3%-8%)." (PMID 21414214, 2011). "Single amino acid substitutions involving codons 12, 13 and 61 of KRAS were identified in 23 of 130 NSCLC (17.7%) overall (18 of 93 adenocarcinomas (19%) and five of 18 NSCLC-NOS (27.7%))." (PMID 21949883, 2011). "Here, 20 adenocarcinomas (10 colorectal, two endometrial and 8 gastric) exhibited co-occurring PIK3CA and KRAS mutations." (PMID 19924296, 2009). "To do so, we compared genetic profiles between EGFR mutated adenocarcinomas (ADC) and KRAS mutated ADC from 24 women with localized lung cancer." (PMID 18549475, 2008). "We note that, to our knowledge, this is one of the first reports describing morphologic switching from adenocarcinoma to sarcomatoid cancer with an epithelial‐to mesenchymal transition (EMT) mechanism in a patients with KRAS G12C–mutant NSCLC who was undergoing sotorasib therapy." (PMID 40445863, 2025). "Although some nuclei showed PTC-like chromatin clearing, negative staining for TTF1 and GATA3 and the absence of KRAS/NRAS mutations ruled out mesonephric-like adenocarcinoma." (PMID 40959354, 2025). "Notably, we identified an exceptionally rare case involving four co-occurring KRAS mutations—G12D, G13D, Q61R, and A146T—in a 60-year-old male patient diagnosed with stage IVB adenocarcinoma (T4, N3, M1c)." (PMID 41153394, 2025). "In the present study (mostly Asian cases), the frequency of KRAS mutations was significantly higher in HNF4α-positive adenocarcinomas (39.4%, 13/33 cases) than in HNF4α-negative adenocarcinomas (9.2%, 19/207 cases)." (PMID 38710944, 2025). "In addition, a previous report has demonstrated that high microsatellite instability (MSI-high) and mutations in genes, such as KRAS, PIK3CA, and PTEN, are associated with rectal endometriosis-associated adenocarcinoma." (PMID 40065885, 2025). "There are well-known facts on the association of NSCLC genotypes with such factors, e.g., EGFR mutations and ALK fusions prevail in female patients with adenocarcinoma of younger age and no history of smoking, while KRAS mutations are more common in smokers." (PMID 40809430, 2025). "Our case had a G12D KRAS mutation in exon 12, reported to be more common in adenocarcinomas from never‐smoker females and to have better progression‐free survival with conventional chemotherapy, but inferior responses to immunotherapy." (PMID 39311155, 2025). "In NSCLC patients harboring KRAS mutations, IL-1β expression did not significantly affect OS in the overall population, adenocarcinoma or SCC subgroups." (PMID 40940992, 2025).
adenocarcinoma (continued). "Until now, there was no registered targeted therapy for the KRAS mutations, which affect 30% of adenocarcinomas." (PMID 38605928, 2024). "In the case of adenocarcinoma, potential targets include KRAS, EGFR, ALK, ERBB2, and/or BRAF." (PMID 38994972, 2024). "Moreover, JAK1 inhibition has been shown to reduce the progression of KRAS mutant adenocarcinoma in mice." (PMID 38706597, 2024). "KRAS and MET mutations occur in older age populations with smoker status and adenocarcinoma." (PMID 38605928, 2024). "An evaluation of therapeutically targetable mutations such as EGFR, ALK, and KRAS, as well as chromosomal rearrangement and fusion of EML4, identified increasing odds of presenting these mutations in adenocarcinoma and NS compared to NSCLC and smokers, respectively." (PMID 37686122, 2023). "This new connection between KRAS and JAK-STAT signalling might be of clinical relevance as JAK1 inhibition has been shown to reduce murine KRAS mutant adenocarcinoma progression." (PMID 37627169, 2023). "Therefore, high EZH2 can indicate lower PRC2 function, and our mouse model and in vitro data show that one result of lowering PRC2 function in KRAS-driven adenocarcinomas is to de-repress FOXP2." (PMID 36670102, 2023). "In a heterogeneous meta-analysis of 23 NSCLC chemotherapy-based studies, 2631 patients with KRAS mutations and an adenocarcinoma subtype had poor prognoses, with a statistically worse overall survival than patients without KRAS mutations." (PMID 37373999, 2023). "The most mutated immunophenotypes of adenocarcinomas were the undefined (1 KRAS; 2 PIK3CA, and 1 BRAF) and the biliopancreatic (2 KRAS and 1 BRAF), followed by the gynecological immunophenotype (1 case with concomitant KRAS and PDGFRA missense mutation and 1 with PIK3CA mutation)." (PMID 36346458, 2023). "KRAS alterations, which were one of the few genomic associations with improved PFS, associated with a history of tobacco exposure, adenocarcinoma histology, and trended toward higher PD-L1 expression in the MDACC-primary cohort, consistent with a more ICI-responsive clinical phenotype." (PMID 36755027, 2023). "For KRAS wild-type tumors, adenocarcinoma (50%) and squamous (43%) histology were equally likely." (PMID 37040387, 2023). "Limited data were available for SCLC, LCNEC, and KRAS mutant adenocarcinoma." (PMID 36136862, 2022). "KRAS mutation may induce PD-L1 expression through phospho-ERK signaling, making ICI an interesting therapeutic strategy in KRAS-mutant adenocarcinomas." (PMID 36275910, 2022). "EGFR (Arg255Gln), EGFR (Ala647Thr), EGFR (Leu858Arg), KRAS (Gly12Cys), ALK (Pro254Thr), ALK (Trp288Ser), ALK (Glu797Lys), ROS (Glu1902Lys), PIK3CA (Met1043Ile), ROS (Leu567Val), and ROS (Phe1153Leu) mutations were present only in patients with adenocarcinoma." (PMID 36422072, 2022). "The KRAS p.G12C single-nucleotide variant, with glycine replaced by cysteine at codon 12, is the most recurrent variant in NSCLC, with a prevalence of nearly 13% in adenocarcinoma histotype." (PMID 35743191, 2022).
adenocarcinoma (continued). "Notably, when using cut-off values between 1–49%, KRAS mutant adenocarcinoma and SCLC both had positive PD-L1 expression in at least 25% of cases." (PMID 36136862, 2022). "RAS-dependent mTORC2 activity would preclude the use of an mTORC1-exclusive inhibitor, and these data may explain why we observed little synergy between everolimus and trametinib in KRAS-dependent adenocarcinoma cell lines." (PMID 36115844, 2022). "Gene mutations could be safely demonstrated from the effusion cfDNA fraction obtained from adenocarcinoma patients, 3/36 EGFR, 9/36 KRAS and 1/36 BRAF gene variants were detected." (PMID 34257581, 2021). "In addition, NECs share mutations (i.e. KRAS; SMAD4 in the pancreas, BRAF and K-Ras in the colon) with respective adenocarcinomas." (PMID 33855635, 2021). "In this study, sEVs were isolated from MPE fluid of four NSCLC patients, whose tumors were of adenocarcinoma histology and clinically validated to harbor EML4-ALK-fusion (PE002), KRAS-mutation (PE009), or mutations in the kinase domain of EGFR (PE011 and PE020)." (PMID 33671772, 2021). "Previous studies have found that concomitant KRAS and EGFR mutations may increase the cell death rate of adenocarcinoma cells through hyperactivation of ERK signaling." (PMID 34921211, 2021). "KEAP1 mutations often occur concurrently with KRAS mutations in adenocarcinomas, however can occur independent of KRAS particularly in SCC." (PMID 34745994, 2021). "Notably, these results were limited to the KRAS wild-type squamous cell carcinoma and adenocarcinoma, whereas in adenocarcinoma histotype the effect of epigenetic silencing of KEAP1 was also observed in the EGFR mutated subpopulation." (PMID 35004317, 2021). "Activating KRAS mutations in adenocarcinoma are usually found in smokers and unlike other oncogene-driven lung cancers, they frequently appear with other major genetic co-mutations." (PMID 33272262, 2020). "The higher mut-KRAS frequency could be due to the fact that our cohort consisted solely of adenocarcinomas from Caucasian individuals treated with checkpoint inhibitor immunotherapy, thus excluding the patients with targetable mutations." (PMID 33322500, 2020). "Our data showed that ALK, ROS1, BRAF or KRAS gene alterations were significantly more frequent in adenocarcinomas with a mucus‐producing component or micropapillary component, and these two components could be a nonpredominant component in some cases." (PMID 32729257, 2020). "KRAS and BRAF mutated CRCs are associated with distinct clinicopathological features according to a large cohort of CRC in Western entity, where RAS mutation is associated with male gender and classical adenocarcinoma subtype." (PMID 32582557, 2020). "Regarding targetable molecular alterations, adenocarcinomas with STAS have been related to wild type epidermal growth factor receptor (EGFR), ALK rearrangement and Kirsten rat sarcoma viral oncogene homolog (KRAS) mutation." (PMID 32564261, 2020). "A meta‐analysis from 28 studies including 3620 patients suggested a lower survival rate of KRAS‐mutated adenocarcinoma (HR = 1.35, 95% CI: 1.16–1.56, P = 0.01), while not in squamous cell carcinoma." (PMID 33022831, 2020).
adenocarcinoma (continued). "Interestingly, the mutant KRAS-driven GBCs predominantly led to adenocarcinomas with tubular structures whereas the ERBB2-driven GBC frequently showed a pronounced tubulo-papillary/papillary differentiation." (PMID 31795490, 2019). "Using the KRasG12V mutant to transform murine lung cells Mainardi and coworkers have reached the conclusion that only SPC+ type II cells are permissive to the transforming activity of this KRAS mutant, first forming hyperplastic lesions, progressing first to adenomas and then to adenocarcinomas." (PMID 30060526, 2018). "Thus, mutant KRAS expression in the context of the APC-mutant colonic epithelium is sufficient to induce dysplastic adenocarcinomas." (PMID 29652830, 2018). "Combination therapy trials with docetaxel (GALAXY 1 and 2) led to better outcomes in patients with adenocarcinomas, than docetaxel single agent therapy, but not in the subgroup of KRAS‐mutated tumors." (PMID 29797762, 2018). "The pathological evaluation revealed KRAS-mutant adenocarcinoma with the final stage of T4bN1M0." (PMID 30155335, 2018). "Although both of thee patients were found to have a substitution mutation in KRAS, a driver mutation that comprises roughly 25% of all adenocarcinoma cases, it has no targetable therapy." (PMID 30042820, 2018). "In our clinical study, we were not able to appreciate a correlation between KRAS status and stable disease, likely because our sample size was small and none of the patients with adenocarcinoma had a KRAS mutation." (PMID 30647837, 2018). "In adenocarcinoma, 10.6% of patients (50.3% if including KRAS) could potentially be eligible for emerging therapeutics, in addition to the 15.3% of patients eligible for standard EGFR or ALK inhibitors." (PMID 28415793, 2017). "The key words associated with a higher probability of arising from a report of a KRAS patient (p < 0.01) clearly indicated more aggressive adenocarcinoma, with words like “numerous”, “several”, “innumerable”, “confluent”, “metastas(es)”, and “hypoattenuat(ing)”." (PMID 28869500, 2017). "In adenocarcinoma, this analysis suggested that 10.6% (50.3% if including KRAS) of cases could be eligible for emerging targeted treatments, beyond the 15.3% of cases eligible for standard EGFR or ALK targeted therapy." (PMID 28415793, 2017). "EGFR and KRAS mutations were simultaneously found in 16.7% and 33.3% of HER2-overexpressing adenocarcinomas, respectively, as well as in 52.2% and 6.5% of HER2-amplified adenocarcinomas, respectively." (PMID 28146588, 2017). "In agreement with the previous study, our results suggest that KRAS and GNAS mutational pattern may represent different pathways in the IPMN-adenocarcinoma sequence." (PMID 27512631, 2016). "The frequency of KRAS mutations was 20.8 % in male patients and 33.2 % in female patients, 8.3 % in never smokers and 32.7 % in ever smokers, 29.9 % in adenocarcinoma tumors and 20.8 % in other NSCLC tumors." (PMID 25902737, 2016). "All patients had stage IV disease at the time crizotinib treatment was initiated, and all tumors were adenocarcinomas with no EGFR/KRAS mutations." (PMID 27418132, 2016). "In addition, KRAS mutations, as well as other driver mutations including EGFR variants, have been shown to be either clonal or sub-clonal in NSCLC adenocarcinoma." (PMID 27448974, 2016). "Because we found a higher frequency of EGFR/KRAS mutations in NSCLC cell lines with high PD-L1 expression (p < 0.001), we evaluated the relationships between downstream signals and PD-L1 expression, particularly in three KRAS-mutant adenocarcinoma cell lines." (PMID 27846317, 2016).